PPP2CA (protein phosphatase 2 catalytic subunit alpha)
Diseases named in the same sentence as PPP2CA in open-access papers (continued):
Sharing a sentence is not in itself a finding about the gene and the disease.
gastric cancer (4 papers, 2017 to 2024). A primary or metastatic malignant neoplasm involving the stomach. "Taken together, our study found that the minor allele [A] of rs13187105 was associated with an increased risk of gastric cancer and meanwhile associated with decreased PPP2CA expression." (PMID 28904398, 2017). "In this study, we genotyped 3 tag SNPs in PPP2CA and evaluated their associations with risk of gastric cancer in a case-control study including 1,113 cases and 1,848 controls in a Chinese population." (PMID 28904398, 2017). "Our study was the first to explore the associations between genetic variants in PPP2CA and risk of gastric cancer." (PMID 28904398, 2017). "In the present study, we conducted a case-control study of 1,113 patients with gastric cancer and 1,848 cancer-free controls in a Chinese population to evaluate the associations of three tagging SNPs in PPP2CA with risk of gastric cancer." (PMID 28904398, 2017). "We found that rs13187105 in PPP2CA was significantly associated with an altered risk of gastric cancer." (PMID 28904398, 2017). "Targeting the YTHDF2/PPP2CA axis may be a potential therapeutic strategy against gastric cancer and YTHDF2 might become a hopeful diagnostic biomarker for this disease in the future." (PMID 36870954, 2023). "Therefore, we hypothesized that genetic variants in PPP2CA might influence susceptibility of gastric cancer." (PMID 28904398, 2017). "Therefore, the decreased expression of PPP2CA might be partially responsible for the observed association between rs13187105 and the risk of gastric cancer." (PMID 28904398, 2017). "Knockdown of PPP2CA mitigated GC cells’ cisplatin sensitivity originally caused by YTHDF2 up-regulation as presented by CCK8 analysis, prompting that YTHDF2/PPP2CA regulatory axis may play a partial role in the drug sensitivity of gastric cancer cells." (PMID 36870954, 2023). "More importantly, we suggested that YTHDF2 could suppress the progression of gastric cancer via regulating PPP2CA and exert a tumor suppressor effect in an m6A-independent manner for the first time." (PMID 36870954, 2023). "Furthermore, we used public databases to compare mRNA level of PPP2CA in gastric tumor tissues with that in adjacent normal tissues, and to explore potential function of the SNPs on gastric cancer development." (PMID 28904398, 2017). "This article is aimed at exploring the relationship between the phosphatase 2A catalytic subunit Cα (PP2Acα, encoded by PPP2CA) and methyltransferase-like 3 (METTL3) in the malignant progression of gastric cancer (GC)." (PMID 34485508, 2021). "However, studies of the association between genetic variants in PPP2CA and risk of gastric cancer are lacking." (PMID 28904398, 2017). "So far, the basic research about stomach cancer has not involved PP2Acα/PPP2CA except that PP2Acα plays an antineoplastic role through the ATM/METTL3 Axis in Cheng’s research." (PMID 36870954, 2023). "The results showed that mRNA levels of five DEGs were significantly (p < 0.05) upregulated in gastric cancer samples while only one DEG, PPP2CA, showed not significantly different (p > 0.05) expression between affected and normal tissues." (PMID 39434198, 2024).
glioma (4 papers, 2015 to 2023). A benign or malignant brain and spinal cord tumor that arises from glial cells (astrocytes, oligodendrocytes, ependymal cells). "MTDH promotes miR-130b expression and subsequently downregulates ceRNAs (PTEN, PPP2CA and SMAD7) to induce EMT-like process of glioma cells." (PMID 28107197, 2017). "MiR-130b promoted EMT-like change and invasion of glioma cells through targeting multiple EMT-related genes, including PTEN, PPP2CA and SMAD7." (PMID 28107197, 2017). "In conclusion, we demonstrate that in glioma cells MTDH acts as a co-activator for NF-kB to upregulate miR-130b expression, which in turn suppresses PTEN, PPP2CA and SMAD7 expression." (PMID 28107197, 2017). "Furthermore, miR-130b promoted glioma EMT-like change by targeting PTEN, PPP2CA and SMAD7, and PTEN acted as the ceRNA for PPP2CA and SMAD7 to inhibit EMT-like change of glioma cells." (PMID 28107197, 2017). "In addition, PTEN acted as the competing endogenous RNA (ceRNA) to affect PPP2CA and SMAD7 expression, and inhibited EMT-like change in glioma cells." (PMID 28107197, 2017). "In addition, we identified PTEN as the miR-130b target that functions as the ceRNAs of PPP2CA and SMAD7 and exhibits inhibitory effects on glioma EMT-like process and invasion." (PMID 28107197, 2017). "Thus MTDH may regulate the expression of miR-130b-ceRNAs (PTEN/PPP2CA/SMAD7), which in turn regulate EMT-like process and glioma invasion." (PMID 28107197, 2017).
Intellectual disability (4 papers, 2022 to 2026). "We uncovered missense mutations in exon two and three that add to spectrum of likely deleterious PPP2CA mutations associated with neurodevelopmental disorder and intellectual disability." (PMID 37056996, 2023). "Although the family pedigree of the girl did show some relatives with intellectual disability or autism, we can almost certainly attribute her condition to this new, pathogenic, de novo PPP2CA variant, and not to any other familial, genetic cause." (PMID 36531959, 2022).
neuroblastoma (4 papers, 2011 to 2025). Neuroblastoma (NB) is the most common solid, extracranial childhood tumor. "similarly, in neuroblastoma cells, reduction of PPP2CA decreases cell growth." (PMID 40959281, 2025).
pancreatic cancer (4 papers, 2019 to 2024). "Among all the PPPcs, PPP1CB, PPP1CC, PPP2CA, PPP2CB, PPP3CB, and PPP5C had tight associations with at least one of the pancreatic cancer related genes in that list." (PMID 33270085, 2021). "Results of the present study suggest that PPP1CA, PPP1CB, PPP2CA, PPP2CB, and PPP3CA have deleterious effects but PPP3CB, PPP5C, and PPP6C have beneficial effects on pancreatic cancer." (PMID 33270085, 2021). "Data from THPA and patients with pancreatic cancer enrolled in our hospital also confirmed the prognostic value of PPP1CA, PPP1CB, PPP2CA, PPP2CB, PPP3CA, PPP3CB, and PPP6C at the protein level." (PMID 33270085, 2021). "In recent years, it has been reported that PPP1CA, PPP1CB, PPP2CA, PPP2CB, and PPP3CA accelerate the progression of pancreatic cancer, while PPP3CB, PPP5C, and PPP6C hinder PAAD progression." (PMID 34125004, 2021). "In addition, only PPP3CB and PPP6C showed favorable prognostic values with regard to protein level, whereas PPP1CA, PPP1CB, PPP1CC, PPP2CA, PPP2CB, and PPP3CA showed unfavorable prognostic values in pancreatic cancer (P<0.05)." (PMID 33270085, 2021).
cardiac hypertrophy (3 papers, 2018 to 2021). "PPP2CA transgenic mice were protected against isoproterenol-induced cardiac hypertrophy and subsequent cardiac fibrosis, whereas simultaneous expression of HDAC2 S394E in the heart did induce hypertrophy." (PMID 30050113, 2018). "Ad-PPP2CA infection blocked the ISP-induced cardiac hypertrophy, as measured by the heart weight to body weight (HW/BW) ratio or heart weight to tibia length (HW/TL) ratio." (PMID 30050113, 2018). "Those investigators specifically introduced a tamoxifen-inducible deletion of PPP2CA in the heart and observed cardiac hypertrophy and its accompanying fibrosis 2 months after ablation of PPP2CA32." (PMID 30050113, 2018). "Because PPP2CA blocked the hypertrophic stress-induced phosphorylation and activation of HDAC2, we concluded that PPP2CA functions as a phosphatase in association with cardiac hypertrophy." (PMID 30050113, 2018). "We evaluated cardiac hypertrophy and thereby fibrosis in mice expressing PPP2CA (TgPPP2CA)." (PMID 30050113, 2018). "To investigate whether PPP2CA negatively regulated cardiac hypertrophy, we performed a radioisotope-free experiment using L-homopropargylglycine (HPG), a methionine analog that is incorporated into protein during de novo synthesis." (PMID 30050113, 2018). "Unlike CK2α1, nuclear PPP2CA was not changed during the development of cardiac hypertrophy, which suggests that chronic overexpression of PPP2CA, as seen in TgPPP2CA, did not reflect the physiologic condition." (PMID 30050113, 2018).
melanoma (3 papers, 2019 to 2024). A malignant, usually aggressive tumor composed of atypical, neoplastic melanocytes. "In support of a key role for PP2A in regulating BRAF activity, we found that in melanoma cells, depletion of PPP2CA or PPP2R2A led to increased p-S365-BRAF and decreased MEK/ERK activity." (PMID 31015455, 2019).
systemic lupus erythematosus (3 papers, 2015 to 2025). An autoimmune multi-organ disease typically associated with vasculopathy and autoantibody production. "Thus, PPP2CA (PP2AC) is characterized as a lupus susceptibility gene." (PMID 39944077, 2025). "Several studies showed that the promotion of inflammatory bodies’ activation was facilitated by PP2Ac and increase expression of Ppp2ca in T cells significantly contribute to molecular defects in systemic lupus erythematosus." (PMID 40160428, 2025).
Cognitive impairment (2 papers, 2022 to 2026). Abnormal cognition is characterized by deficits in thinking, reasoning, or remembering. "Loss of PP2Acα triggers a cascade of defects that culminate in motor and cognitive impairments resembling human PPP2CA-related disorders." (PMID 41509924, 2026).
gastric tumor (2 papers, 2017 to 2023). "Further analyses showed that rs13187105 [A] was associated with decreased expression of PPP2CA mRNA (P = 5.1 × 10−6), and PPP2CA mRNA was significantly lower in gastric tumor tissues when comparing that in their adjacent normal tissues (P = 0.037)." (PMID 28904398, 2017). "Moreover, PPP2CA expression was lower in gastric tumor tissues compared to that in adjacent normal tissues." (PMID 28904398, 2017).
heart failure (2 papers, 2018 to 2021). Inability of the heart to pump blood at an adequate rate to meet tissue metabolic requirements. "It is noteworthy that the chronic overexpression of PPP2CA, however, aggravated cardiac function and finally led to heart failure." (PMID 30050113, 2018).
Infertility (2 papers, 2016 to 2024). "Knocking out Ppp2ca exon 2 causes changes in testicular morphology and infertility." (PMID 27213341, 2016).
liver cancer (2 papers, 2023 to 2024). An epithelial or non-epithelial malignant neoplasm that arises from the liver. "The PP2Acα (PP2A catalytic subunit Cα, encoded by PPP2CA) is the core enzyme of PP2A, and previous reports revealed that PP2Acα dysfunction plays an important role in the progress of many cancers, such as liver cancer and acute myeloid leukemia." (PMID 36870954, 2023).
microcephaly (2 papers, 2023 to 2024). A congenital or acquired developmental disorder in which the circumference of the head is smaller than normal for the person's age and sex. "A study showed that the conditional knockout of Ppp2ca in the nervous system resulted in severe microcephaly by regulating the signaling transduction of the Hippo-p73 cascade." (PMID 37761890, 2023). "Furthermore, mice with conditional loss of PPP2CA in the central nervous system were reported to exhibit severe microcephaly, cortical atrophy and intellectual learning and memory defects, supporting an important role for PPP2CA in the context of development." (PMID 38450154, 2024).
thyroid cancer (2 papers, 2021). "MiR-650 enhances thyroid cancer cell motility by regulating PPP2CA." (PMID 34290668, 2021).
anaplastic thyroid carcinoma (1 paper, 2022). "In addition, miR-650 overexpressed in anaplastic thyroid carcinoma (ATC), where it promotes the proliferation and motility of cancer cells by targeting Protein Phosphatase 2 Catalytic Subunit Alpha (PPP2CA)." (PMID 35331235, 2022).
COVID-19 (1 paper, 2023). A disease caused by infection with severe acute respiratory syndrome coronavirus 2. "In conclusion, our study provides global insights into the transcriptome profiles of host responses in COVID-19-vaccinated individuals and identifies MAPK1, CDC42, PPP2CA, EP300, YWHAZ and NRAS as hub genes that are significantly correlated with the vaccine response." (PMID 37096063, 2023).
dementia (1 paper, 2014). Loss of intellectual abilities interfering with an individual's social and occupational functions. "Among the six PP2A proteins, three proteins (PPP2R2B, PPP2CA, and PPP2R1A) are also listed in the highly ranked proteins in the dementia network, demonstrating their centrality." (PMID 24908109, 2014).
dilated cardiomyopathy (1 paper, 2018). Cardiomyopathy which is characterized by dilation and contractile dysfunction of the left and right ventricles. "This led us to assume that the dilated cardiomyopathy phenotype is caused by the diversity of the targets of PPP2CA." (PMID 30050113, 2018).
esophageal adenocarcinoma (1 paper, 2021). A malignant tumor with glandular differentiation arising predominantly from Barrett mucosa in the lower third of the esophagus. "High PPP2CA expression in tumors leads to shorter overall survival in both esophageal squamous cell carcinoma (ESCC) and esophageal adenocarcinoma (EAC) patients (p = 0.065 and 0.0085, respectively, log-rank test), suggesting the important role of PP2A in ESCC progression." (PMID 34638252, 2021).
fungal infections (1 paper, 2024). "Interestingly, our bioinformatics analysis showed that host interactors were enriched in DARPP-32 events at high levels, and other interactors, including RHOA and PPP2CA, prompting us to explore the possibility of non-neurological functions of DARPP-32, especially its role in fungal infections." (PMID 38413612, 2024).
leukaemias (1 paper, 2019). "PP2A inhibition is essential for leukaemias driven by oncogenic mutant c-KIT and FLT3, with the PP2A-C catalytic subunit (PPP2CA) oxidised at cysteine residues, Cys266/269, contributing to the loss of the phosphatase activity under oxidative stress." (PMID 31795243, 2019).
lung adenocarcinoma (1 paper, 2020). A carcinoma that arises from the lung and is characterized by the presence of malignant glandular epithelial cells. "Other group reported that the mutants of truncated STRIP2, which were found in lung adenocarcinoma and uterine carcinoma, loss the ability to bind with PPP2CA and drove cell contraction, underlying their role in cancer." (PMID 32754603, 2020).
osteosarcoma (1 paper, 2021). A usually aggressive malignant bone-forming mesenchymal neoplasm, predominantly affecting adolescents and young adults. "The reduction of PPP2CA suppressed the proliferation and metastasis of osteosarcoma both in vitro and in vivo." (PMID 33593435, 2021). "PPP2CA, the catalytic subunit of PP2A, was higher expressed in osteosarcoma tissues." (PMID 33593435, 2021).
pulmonary disorder (1 paper, 2022). "Based on pathway enrichment analysis, genes altered in BPD blood cells were mainly enriched in cell cycle regulation and arrest (e.g., PPP2CA, RBL2, CENPU, CCNY, CDK6) and pulmonary disorder and developmental disorders (e.g., AGER, ITGA6, CA4, BACH2, IGFBP2, BMPR2, SKI, DAB2)." (PMID 35484630, 2022).
pulmonary fibrosis (1 paper, 2023). Chronic progressive interstitial lung disorder characterized by the replacement of the lung tissue by connective tissue, leading to progressive dyspnea, respiratory failure, or right heart failure. "Compared with the control group, the BLM-induced pulmonary fibrosis group exhibited significantly higher expression of Fmod and Tgfbr2 mRNA; in contrast, the mRNA expression levels of Bambi, Skp1, Zfyve9, Zfyve16, Ppp2ca, Ppp2r1a, Ppp2r1b, Rps6kb1, and Rps6kb2 were markedly lower." (PMID 38259493, 2023).
renal carcinoma (1 paper, 2025). A carcinoma arising from the epithelium of the renal parenchyma or the renal pelvis. "In contrast, PPP2CA-OE enhanced renal cancer cell migration, invasion, wound healing, and colony formation." (PMID 40959281, 2025). "Moreover, both MKRN2ΔR and ΔCH were poor facilitators of PPP2CA degradation in renal cancer cells." (PMID 40959281, 2025).
rheumatoid arthritis (1 paper, 2020). A chronic, systemic autoimmune disorder characterized by inflammation in the synovial membranes and articular surfaces. "The top 50 DEG include genes with variants previously associated with SS (CXCR5), SLE (CXCR5, PPP2CA, and TCF7), and rheumatoid arthritis (FCRL3)." (PMID 32650575, 2020).